YTHDF1 (YTH N6-methyladenosine RNA binding protein F1)
Diseases named in the same sentence as YTHDF1 in open-access papers (continued):
Sharing a sentence is not in itself a finding about the gene and the disease.
tumor (continued). "With TCGA cohort, we examined the four common m6A readers (YTHDF1, YTHDF2, YTHDF3, and YTHDC1) in LUAD tumor samples and normal samples, and found YTHDF1 highly expressed in tumor tissues." (PMID 32195181, 2020). "Specifically, HNRNPC, YTHDF1, YTHDF2, METTL3, RBM15, YTHDF3, and KIAA1429 are highly expressed in tumor tissues." (PMID 32258108, 2020). "Comparisons between adjacent normal and tumor samples identified seven down-regulated (METTL14, WTAP, YTHDC1, YTHDC2, ALKBH5, FTO, and YTHDF2) and one up-regulated (YTHDF1) regulators." (PMID 32500031, 2020). "Following transfection of short hairpin RNA (shRNA) targeting YTHDF1, the biological activities of HCC cells were evaluated by Cell Counting Kit-8 (CCK-8), wound-healing, Transwell, flow cytometry, and xenograft tumor assays, respectively." (PMID 33363211, 2020). "Therefore, targeting YTHDF1 directly or through its binding to the translational initiation factors might be able to prevent activation of translation and subsequent products of integration of virus genome in the tumor cells." (PMID 31947544, 2020). "We examined the expression of 17 m6A-related genes in GEO database, and found that WTAP, RBM15, YTHDF1, and YTHDF2 were differently expressed in tumor tissue compared with control tissue." (PMID 32814762, 2020). "For the m6A methylation readers, the expression of HNRNPC, YTHDF1, and YTHDF2 was also significantly increased in higher tumor grade and stage." (PMID 32850303, 2020). "Mechanistically, TFRC was identified as a direct target of YTHDF1 in HPSCC cells and promoted iron metabolism, thereby increasing tumor growth and proliferation." (PMID 33204330, 2020). "Knocking down the expression of YTHDF1 significantly inhibited the CRC cell's tumorigenicity in vitro and murine xenograft tumor growth in vivo." (PMID 31131257, 2019). "We show that YTHDF1 inhibition suppresses NSCLC cell proliferation, colony formation, xenograft tumor formation, and de novo lung ADC progression." (PMID 31653849, 2019). "In the DDP treatment tumor groups, dramatically higher proliferation as measured by Ki67 IHC, and lower overall apoptosis indicated by CC3 IHC, in YTHDF1 shRNA tumors were also detected compared with control tumors." (PMID 31653849, 2019). "In addition, the YTHDF1 and LGR5 proteins were consistently upregulated in CRC tumor tissues compared with paired adjacent normal tissues in the TCGA database." (PMID 41423446, 2025). "HK2 can be directly mediated by the m6A modifiers METTL3, YTHDF1, IGF2BP2, FTO and ALKBH5 in colorectal cancer and cervical cancer, leading to increased glycolysis, upregulated aerobic respiration in mitochondria and tumor progression." (PMID 41373022, 2025). "YTHDF1 affects the recruitment and activation of immune cells such as macrophages, NK cells, and CD8+ T cells, thereby altering the immune cell composition within the tumor." (PMID 39911396, 2025). "Furthermore, single cell sequencing data from GC patients revealed an inverse correlation between the expression of YTHDF1 and YTHDF2 and that of IRF1, particularly within tumor cells, T cells, and macrophages." (PMID 39587835, 2025). "Together, these findings substantiate the role of YTHDF1 in enhancing the translational efficiency of RNF7, thereby facilitating the ubiquitin-mediated degradation of the p27 proteins, and leading to robust tumor growth." (PMID 40251202, 2025). "A recent study demonstrated that YTHDF1 is highly expressed in response to N-methyl-N-nitrosourea (MNU) stimulation, subsequently promoting the translation of the HSPH1 protein in an M6A-dependent manner, which facilitates tumor cell proliferation." (PMID 41312360, 2025). "The seemingly contradictory roles of YTHDF1 and YTHDF2 in tumor immune regulation may arise from their context-dependent functions and cell-type specificity." (PMID 41403953, 2025).
tumor (continued). "In tumor cells, YTHDF1 enhances translation of the lysosomal/acidic hydrolase genes, promoting antigen and MHC-I turnover; deleting YTHDF1 stabilizes MHC-I at the surface, improves CD8+ priming, and heightens responsiveness to checkpoint blockade in multiple mouse systems." (PMID 41280938, 2025). "Therapeutically, targeting of YTHDF1 in vitro and in vivo with vesicle-like nanoparticle (VNP)-encapsulated siYTHDF1 or YTHDF1 selective inhibitor salicylic acid C (SAC) suppressed tumor growth and synergistically enhanced OXA and 5-FU treatment efficacy in vivo." (PMID 41423446, 2025). "The overall message is consistent across compartments—YTHDF1 acts as a brake on T-cell entry and activation—even though the dominant downstream pathway (lysosomal antigen/MHC-I turnover in tumor cells versus STING erosion in DCs) differs by cell type and stimulus." (PMID 41280938, 2025). "The lack of YTHDF1 expression in classical dendritic cells heightened the in vivo cross-presentation of tumor antigens and the cross-priming of CD8+ T cells." (PMID 38830900, 2024). "Given that irradiated tumor cells induce IFN-I production in DCs, we proposed that IFN-I signaling could be involved in the IR-induced increase in YTHDF1 expression in DCs." (PMID 39325547, 2024). "In a mouse tumor model, mice lacking YTHDF1 exhibited heightened antigen-specific CD8+ T cell antitumor capacity." (PMID 39072324, 2024). "We then inoculated B16 cells into immunocompetent C57BL/6 mice and observed that the KO of Ythdf1/3 alone did not affect tumour growth compared to the control group." (PMID 39568154, 2024). "The absence of YTHDF1 led to the inhibition of cathepsins, thereby enhancing cross-presentation by DCs and contributing to the anti-tumor immune response." (PMID 38830900, 2024). "Additionally, we observed that most high-expressed m6A regulatory factors in tumor tissues had CNV gains, such as VIRMA, ZNF217, and YTHDF1." (PMID 39020010, 2024). "The structure includes a shell of DSPE-modified RGD peptides targeting integrin receptors on tumor cells and carboxymethyl mannose targeting CD206 receptors on macrophages, with a core of chitosan adsorbing m6A reading protein YTHDF1 siRNA and chromium nanoparticles (Cr NPs)." (PMID 38898486, 2024). "To assess whether the antitumor effects of IR in Ythdf1-cKO mice depend on CD8+ T cells, we examined B16-OZ tumor–infiltrating T cells by flow cytometry." (PMID 39325547, 2024). "Moreover, the animal experiments further confirmed that KIAA1429 silencing diminished levels of YTHDF1, FOXM1, HK2, ENO1, and LDHA and suppressed tumor growth." (PMID 39060874, 2024). "Further study showed that the efficacy of combined YTHDF1 knockdown and anti-PD-L1 treatment was quite good, superior to that of single agent control group, and combining m6A with immune checkpoint inhibitor (ICI) treatment is promising in tumor therapy." (PMID 38711100, 2024). "In addition, the m6A readers, including YTHDF1/2/3, HNRNPC, HNRNPA2B1, RBMX, PRRC2A, and CPSF6, also demonstrated a higher expression in the tumor samples compared to the normal tissues." (PMID 38610981, 2024). "We detected the expression of YTHDF1 or IGF2BP1 in normal epithelial and tumor cell lines." (PMID 39185313, 2024). "YTHDF1 and YTHDF2 knockdown enhanced PD-L1 expression in tumor cells." (PMID 36810108, 2023). "MDNP/siYTH polyplexes, employed for the non-viral delivery of YTHDF1 siRNA into DCs, displayed the best tumor growth inhibition in the MDNP/siYTH polyplexes + aPD-L1 combinational treatment mice group." (PMID 36960074, 2023). "The mRNA expression levels of YTHDC2, YTHDF1, YTHDF3, IGF2BP1, and IGF2BP3 were significantly increased in tumour tissues compared with paired normal breast tissues, while the METTL14, WTAP, FTO, and IGF2BP2 expression levels were significantly decreased in tumour tissues." (PMID 36632454, 2023).
tumor (continued). "We further performed a comprehensive analysis of 33 types of tumors from the TCGA and found that YTHDF1 RNA showed a significantly negative correlation with the immune score in 26 of the tumor types." (PMID 36650153, 2023). "Also in HCC, HIF1α-induced expression of YTHDF1 drives ATG2A and ATG14 translation, two autophagy-related genes, promoting tumor progression." (PMID 37369946, 2023). "These outcomes suggest that the tumor suppressor effect of ANXA10 is related to m6A; ANXA10 may regulate HNRNPA2B1, IGF2BP3, METTL3, RBM15, YTHDF1 and YTHDF2 to affect the methylation level of LIHC." (PMID 36709331, 2023). "YTHDF1-mediated glutamine metabolism via GLS1 has been shown to promote cisplatin chemoresistance in CRC cells, while the combination of YTHDF1 silencing and cisplatin leads to a synergistic effect in suppressing tumor growth." (PMID 36650570, 2023). "Numerous studies have shown that YTHDF1 plays an important role in tumor biology and nontumor lesions by mediating the protein translation of important genes or by affecting the expression of key factors involved in many important cell signaling pathways." (PMID 36650570, 2023). "In this review, we aim to present the latest comprehensive insights into the multifaceted involvement of YTHDF1, a member of the YTHDF family, in various aspects of tumor cell metabolism, with a particular focus on elucidating its unique characteristics in tumor cell metabolic reprogramming." (PMID 38202722, 2023). "Similar results were observed in CRC, mice-bearing YTHDF1-knockdown CT26 and MC38 tumor cells showed significantly reduced tumor growth rate and weight, and the overall survival of mice receiving the combination therapy was dramatically prolonged compared with those in either monotherapy group." (PMID 36960074, 2023). "YTHDF1 assumes a significant role in this context, as it has been reported to govern the translation process of crucial regulatory factors CDK2, CDK4, and CCND1, thereby regulating the G1 to S phase transition of tumor cells in NSCLC." (PMID 38202722, 2023). "Histological staining of tumor sections with hematoxylin and eosin (H&E) showed that the tumor lesion area in mouse limbs was greatly reduced by knockdown of METTL3 and YTHDF1 along with reduced tartrate resistant acid phosphatase (TRAP), indicative of clear decreases in osteoclast activity." (PMID 36923927, 2023). "Similarly, YTHDF1 was reported to enhance the translation of methylated YAP transcripts and participate in the tumor progression of OS." (PMID 36650570, 2023). "Mice lacking YTHDF1, a protein which binds to N6‐methylated adenosine residues (m6A) in mRNAs showed enhanced anti‐tumour CD8 T cell responses." (PMID 35220694, 2022). "Our findings affect the m6A-related gene YTHDF1 and dendritic cells in immunity, and METTL3 enhanced the response to anti-PD-1 treatment, which suggests that these lncRNAs enhance the effect of tumor immunotherapy by regulating m6A-related target genes." (PMID 36168326, 2022). "So, the absence of YTHDF1 in classical dendritic cells enhanced the cross-presentation of tumor antigens and the cross-primers of CD8+ T cells in vivo without affecting DCs development or activation." (PMID 35590394, 2022). "In addition, YTHDC1, YTHDF1, YTHDF2, IGF2BP3, HNRNPA2B1 and NKAP were confirmed by two databases to be positively correlated with tumor stage, which deserved more attention in the treatment of HCC." (PMID 35963644, 2022). "Deletion of YTHDF1 leads to cross presentation of tumor antigens and in vivo CD8+ T cell cross primers without affecting DCs development or activation." (PMID 35590394, 2022). "For example, YTHDF1 has been shown to play an important role in tumour immune escape by regulating the levels of CD8+ T cells and NK cells, thereby affecting the efficacy of tumour immunotherapy." (PMID 36434140, 2022).
tumor (continued). "FRAS1 silence or YTHDF1 silence could rescue the elevated NSCLC cell proliferation, colony formation, and tumor growth induced by METTL3 overexpression in vitro and in vivo." (PMID 36008805, 2022). "Second, we did not establish a metastasis model to explore the effect of YTHDF1 on tumor metastasis in vivo." (PMID 35156522, 2022). "In a study of NSCLC, YTHDF1 and YTHDF2 were associated with a good prognosis of NSCLC patients, and down-regulation of YTHDF1 and YTHDF2 could up-regulate the expression of PD-L1 and reverse the tumor suppressive microenvironment." (PMID 36618420, 2022). "Consistent with the trends in YTHDF1 and PKM2 expression, the tumor growth in the agomiR-16-5p treatment group was evidently inhibited, in which the average tumor volume after 24 days of administration was about 1/4 of that of the control group (Original western blot data 15)." (PMID 35319018, 2022). "The results of immunohistochemical analysis also showed that after miR-16-5p treatment the expression levels of YTHDF1 and PKM2 in tumor tissues were significantly down-regulated, indicating that miR-16-5p can selectively target the YTHDF1-PKM2 signal axis to inhibit tumor growth." (PMID 35319018, 2022). "In classical DCs, the absence of YTHDF1 enhances the cross-presentation of tumor antigens and the cross-priming of CD8+ T cells in vivo." (PMID 34630412, 2021). "We chose some regulators for RT-qPCR validation, and the qPCR results revealed that METTL3, METTL14, and FTO had consistently low expression in 33 paired samples with TCGA data, while YTHDF1 and YTHDF3 showed increased expression in tumor samples compared to adjacent tissues." (PMID 34804948, 2021). "The TME with low YTHDF1 expression contained higher levels of CD8+ T cells and natural killer (NK) cells in a mouse model, and enhanced the ability to DCs in cross-present of tumor antigens." (PMID 34026603, 2021). "Furthermore, these specific mRNAs were read by YTHDF1, and the spicing and translation of cancer growth-related genes were induced, thereby promoting LUAD tumor growth." (PMID 32195181, 2020). "YTHDF1 was highly expressed in ovarian cancer and targeted at EIF3C to enhance its translation efficiency via an m6A-dependent manner; therefore, affecting the overall translational output and regulating tumor cells proliferation, migration, and invasion." (PMID 32276589, 2020). "Most increased regulators in tumor cases compared to normal cases were YTHDF2 (p < 0.001), FTO (p < 0.001), YTHDC1 (p < 0.001), YTHDC2 (p < 0.001), YTHDF1 (p < 0.001), KIAA1429 (p < 0.001), METTL3 (p < 0.010), WTAP (p < 0.001), RBM15 (p < 0.001), HNRNPC (p < 0.001), and ALKBH5 (p = 0.001)." (PMID 32733931, 2020). "Notably, the protein levels of YTHDF1 exhibit a negative correlation with the infiltration of CD8 + T cells in tumor tissues of CRC and melanoma patients." (PMID 39987091, 2025). "Notably, YTHDF1 and YTHDF2 promote the recruitment of tumor-infiltrating lymphocytes (TILs), enhancing immune surveillance while simultaneously suppressing PD-L1 expression to facilitate immune cell-mediated tumor destruction, thus establishing an inflammatory tumor milieu." (PMID 40740874, 2025). "FTO inhibition + radiotherapy enhanced tumor control without worsening normal-tissue toxicity; reader targeting (YTHDF1/2) + RT or RT+ICB amplified STING–IFN-I signaling and T-cell priming; METTL3 inhibition combined with venetoclax overcame acquired resistance in AML." (PMID 41280938, 2025). "The silencing of YTHDF1 using lipid nanoparticles encapsulated with siYthdf1 (LNP-siYthdf1), in conjunction with anti-PD-1 therapy, synergistically inhibited MDSC recruitment and activated CD8 + T cell function in mouse models of NASH-HCC, thereby reducing tumor burden and growth." (PMID 39987091, 2025).
tumor (continued). "Moreover, both methionine-restricted diets and YTHDF1 knockdown were shown to reduce m6A methylation and translation of immune checkpoints, including PD-L1 and VISTA, in cancer cells, thereby restoring CD8 + T cell infiltration into the tumor." (PMID 39987091, 2025). "Moreover, our results showed that intratumoral (i.t.)treatment of 2′3′-cGAMP (STING agonist) increased the expression of YTHDF1 in tumor-infiltrating DCs in WT mice but not in Sting-KO mice." (PMID 39325547, 2024). "In experiments with tumor-bearing mice, M.RGD@Cr-CTS-siYTHDF1 NPs, when exposed to laser irradiation, effectively killed tumor cells, disrupted the TME, delivered siYTHDF1 to TAMs, silenced the YTHDF1 gene, and shifted the STAT3-STAT1 equilibrium by reducing STAT3 and enhancing STAT1 expression." (PMID 38898486, 2024). "YTHDF1 expression in BMDCs from Ifnar1-KO mice was not increased by irradiated tumor cells." (PMID 39325547, 2024). "Zhang reported that YTHDF1 can be mediated by METTL14 overexpression, enhancing the stability of Pten mRNA in an m6A-dependent manner and thereby inhibiting the proliferation and migration of tumor cells, activating AKT signaling, and suppressing tumor progression." (PMID 38202722, 2023). "Whereas YTHDF1 depletion limited lysosomal proteolysis in tumor cells, subsequently enhancing the MHC-I expression and minimizing the destruction of internalized antigens, which ultimately restored tumor immune surveillance and triggered a robust antitumor immunity." (PMID 36650153, 2023). "Depletion of YTHDF1 suppresses the translation of lysosomal cathepsins in DCs, downregulated cathepsins attenuates antigen degradation and thus enhances cross-presentation to CD8 + T cells, further increased IFN-γ expression in CD8 + T cells upregulates PD-L1 expression in tumor cells." (PMID 36810281, 2023). "YTHDF1 increased the translation of EGFR mRNA via binding to m6 A sites in the 3′-UTR of the EGFR transcript, thus leading to the aberrant activity of downstream signal pathways that could promote tumor progression." (PMID 36835633, 2023). "YTHDF1 exhibits a negative correlation with PD-L1 expression, and may serve as a crucial mediator regulating PD-L1 expression and the tumor immune microenvironment, significantly influencing the development of CC." (PMID 38202722, 2023). "Interestingly, in a lactate-enriched TIME, lactylation drove METTL3 upregulation in tumour-infiltrating myeloid (TIM) cells and enhanced the immunosuppressive function of TIM cells through YTHDF1-mediated Jak1 translation and the subsequent phosphorylation of STAT3." (PMID 36859310, 2023). "Tumor immune infiltrations in YTHDF1-deficient mice contained higher levels of CD8+ cytotoxic T cells and natural killer (NK) cells compared with wild-type mice, indicating that immune surveillance was enhanced in the absence of YTHDF1." (PMID 35590394, 2022). "The authors showed that antibodies targeting PD‐L1 (checkpoint inhibitors), to promote anti‐tumour immunity, were more effective in mice lacking YTHDF1 leading to the suggestion that this methylase could be a therapeutic target alongside checkpoint inhibitors." (PMID 35220694, 2022). "Furthermore, the anti-tumor response is completely abrogated in Ythdf1–/– mice lacking CD8+ T cells, thus highlighting the involvement of m6A modification in the regulation of CD8+ T cells and tumorigenesis." (PMID 35254013, 2022). "YTHDF1 has been identified to be critical for NSCLC proliferation In this study, we found that YTHDF1 was highly expressed in NSCLC tumor tissues compared to normal tissues via UALCAN, indicating that YTHDF1 may play a critical role in m6A-regulated FRAS1 expression." (PMID 36008805, 2022). "However, reports have also shown that YTHDF1 and YTHDF2 can act as tumor suppressors." (PMID 33922187, 2021).